TGFA (transforming growth factor alpha)
Diseases named in the same sentence as TGFA in open-access papers (continued):
Sharing a sentence is not in itself a finding about the gene and the disease.
Sepsis (4 papers, 2013 to 2025). Sepsis is defined as life-threatening organ dysfunction caused by a dysregulated host response to infection. "Cytokines and leptin are increased in severely burned patients, including those cases associated with sepsis and those patients who ultimately do not survive their injuries while basic fibroblast growth factor (bFGF) and transforming growth factor alpha (TGFα) levels are lower in severe cases." (PMID 23762773, 2013). "qRT-PCR validation demonstrated significantly elevated expression of TGFA (P = .0306), GNAQ (P = .0185), and PDSS1 (P = .0052) in septicemia patients." (PMID 41305715, 2025). "TGFA may activate downstream pathways such as Ras-MAPK and PI3K-AKT through the EGFR signaling pathway, a potential metabolic role in sepsis consistent with its significant enrichment in MAPK signaling pathways identified by GSEA analysis (P < .05)." (PMID 41305715, 2025).
gastric ulcer (3 papers, 2009 to 2013). An ulcerated lesion in the mucosal surface of the stomach. "Indeed, it was recently shown that gastric ulcer healing in rats is promoted by cathelicidin-mediated transactivation of epidermal growth factor receptors (EGFR) via the transforming growth factor alpha (TGFα) signaling pathway." (PMID 19728885, 2009).
ischemic stroke (3 papers, 2018 to 2022). A stroke disorder caused by obstruction of blood flow to the brain, due to thrombotic (local blood clot formation) or embolic (due to a blood clot or other material traveling from another site) event. "The striatal infusion of transforming growth factor alpha (TGFα), which is a ligand for EGFR/ErbB1 has exhibited a similar neuroprotection in the rat model of ischemic stroke." (PMID 29342116, 2018).
kidney cancer (3 papers, 2015 to 2021). Primary or metastatic malignant neoplasm involving the kidney. "That finding opens the possibility of exploiting expression of membrane bound TGFα as a novel therapeutic target in kidney cancer." (PMID 34399807, 2021). "Analyses of paired normal-tumoral patient samples showed that active EGFR and TGFα are frequently expressed in kidney cancer." (PMID 34399807, 2021). "Next, and by using similar approaches, the impact of TGFα targeting on the proliferation of kidney cancer cells was studied." (PMID 34399807, 2021). "Exploration of Firebrowse and GEPIA2 databases showed that kidney cancer ranked first with respect to TGFα expression when compared to other tumoral types represented in those databases." (PMID 34399807, 2021). "The expression and prooncogenic functions of the EGFR and TGFα in kidney cancer have already been reported, but only strategies acting on the EGFR have been tested in the clinic." (PMID 34399807, 2021). "We show that reduction of the expression of either EGFR or TGFα by RNAi reduced proliferation of kidney cancer cells." (PMID 34399807, 2021). "Together, these observations indicate that among all EGFR ligands, TGFα is the only one expressed at high levels in kidney cancer." (PMID 34399807, 2021). "Of the tumors present in this database, kidney cancer ranked first with respect to TGFα expression levels." (PMID 34399807, 2021). "HNF4A is known to control cell proliferation in kidney cancer cell lines, and regulates a number of well-known cancer-associated genes to do so (e.g. CDKN1A and TGFA)." (PMID 25961905, 2015). "To explore whether the TGFα/EGFR axis could play a role in the pathophysiology of kidney cancer, we used genetic and pharmacologic approaches to explore the effect of targeting the EGFR on the proliferation of kidney cancer cells." (PMID 34399807, 2021). "Similar analyses showed that kidney cancer ranked first with respect to TGFα expression." (PMID 34399807, 2021). "Moreover, the therapeutic antibody cetuximab or a neutralizing antibody against soluble TGFα reduced proliferation of cellular models of kidney cancer." (PMID 34399807, 2021). "On the other hand, that high grade of uncertainty motivated us to preclinically explore the role of EGFR and TGFα in kidney cancer, as they could be used as druggable targets." (PMID 34399807, 2021). "In fact, the cell proliferation data obtained by genetic as well as the pharmacologic targeting of EGFR and TGFα suggest that acting on this system may be used therapeutically in kidney cancer." (PMID 34399807, 2021). "Comparative RNAseq data of the 37 kidney cancer cell lines represented in such database showed expected variability among their EGFR and TGFA mRNA levels and copy number." (PMID 34399807, 2021). "In the case of TGFα, its pathophysiological role as well as its potential manipulation with therapeutic purposes have not been explored in kidney cancer." (PMID 34399807, 2021).
lymph node metastasis (3 papers, 2000 to 2022). "TGFα is highly associated with axillary lymph node metastasis and low survival rates among BC patients." (PMID 30034618, 2018).
mental disorder (3 papers, 2021 to 2024). A disease that has its basis in the disruption of mental process. "Therefore, future studies should consider the possible role of TGFA in psychiatric disorders." (PMID 33946816, 2021). "Data regarding role of TGFA in psychiatric diseases is lacking; however, it could be advantageous in supporting the neuroprotective effect in the CNS." (PMID 36012250, 2022).
multiple sclerosis (3 papers, 2020 to 2025). A progressive autoimmune disorder affecting the central nervous system resulting in demyelination. "Analyzing cerebrospinal fluid (CSF) samples of Multiple Sclerosis (MS) patients as well as CNS samples of female mice with experimental autoimmune encephalomyelitis (EAE), the animal model of MS, we identify microglia-derived TGFα as key factor driving recovery." (PMID 40537468, 2025).
Parkinson disease (3 papers, 2012 to 2021). A progressive degenerative disorder of the central nervous system characterized by loss of dopamine producing neurons in the substantia nigra and the presence of Lewy bodies in the substantia nigra and locus coeruleus. "In addition, a role for TGFa/EGFR signaling in promoting migration of cells derived from the SVZ was highlighted by TGFa infusion to the dopamine-depleted striatum of rodent models of Parkinson's disease." (PMID 22907990, 2012).
periodontal disease (3 papers, 2016 to 2025). "NGAL expression can be stimulated by many cytokines and growth factors that may contribute to periodontal diseases, such as interleukin-1, IL-17, IL-22, insulin-like growth factor-1, transforming growth factor alpha, and tumor necrosis factor-alpha." (PMID 41040472, 2025).
periodontitis (3 papers, 2016 to 2024). An acute or chronic inflammatory process that affects the tissues that surround and support the teeth. "In addition, it is known that plasma cells produce a variety of pro-osteoclastic factors, such as IL-6, IL-10, Transforming Growth Factor alpha (TGF-α), TGF-β, and matrix metalloproteinases (MMPs), which facilitate the degradation of periodontitis tissues." (PMID 32411181, 2020).
renal fibrosis (3 papers, 2015 to 2023). A final common manifestation of a wide variety of chronic kidney diseases characterized by glomerulosclerosis and tubulointerstitial fibrosis. "Experimental studies have demonstrated the involvement of TGFA in renal fibrosis, as in the model of Ang II-induced renal damage." (PMID 30670929, 2018). "Q-PCR indicated a significant reduction in the expression of renal fibrosis-related genes (fn-1, αSMA, Col1a1, Col3a1, Ctgf, fsp1, KIM) and inflammatory cytokines (Tgfα, Tgfβ, Il-1b, Il-4, Il-6, CD44, CD68) in the kidney of the acetate-treatment group." (PMID 36922584, 2023). "In addition, it has been observed that in knockout mice for TGFA and in mice treated with a specific inhibitor of ADAM17, renal fibrosis induced by Ang II decreases." (PMID 30670929, 2018).
tooth agenesis (3 papers, 2012 to 2017). A tooth disease characterized by failure to develop one or more missing teeth. "Other genes including TGFA, PAX9, FGFRI and IFR6, which had previously been related to oral clefts, were also associated with isolated tooth agenesis, as observed in premolars." (PMID 29167708, 2017).
acanthosis nigricans (2 papers, 2023 to 2025). A melanotic cutaneous lesion that develops in the axilla and other body folds. "Acanthosis nigricans presents as hyperpigmented, velvety plaques in intertriginous areas, which is driven by tumor overproduction of transforming growth factor-alpha (TGF-α) and insulin-like growth factors (IGFs) stimulating epidermal proliferation." (PMID 40867266, 2025).
Arthritis (2 papers, 2012 to 2019). Inflammation of a joint. "TMI-1 has been successfully used in mouse models of arthritis and kidney diseases to target and inhibit ADAM-17-mediated TNFα (Tumor Necrosis Factorα) and TGFα (Transforming Growth Factorα) release, respectively." (PMID 23028451, 2012).
astrocytoma (2 papers, 2022 to 2024). "As in the astrocytoma cells, TGFα was produced in a P2Y11-dependent manner in M2 macrophages, although at a low level, contrasting with the high levels of the known P2Y11 target sTNF-RII." (PMID 38472446, 2024).
cervical (2 papers, 2016 to 2022). "Females having cervicitis (CE) exhibited strong positive relationships between the following: E2 and P4 (0.99; p = 0.009), TGFα and free T3 (0.98; p = 0.03), glucose and P4 (0.98; p = 0.02), glucose and E2 (0.94; p < 0.05), and inhibin and F-T3 (0.97; p = 0.03)." (PMID 36009715, 2022).
Cognitive impairment (2 papers, 2021 to 2023). Abnormal cognition is characterized by deficits in thinking, reasoning, or remembering. "This compound facilitates the release of growth factors that activate ErbB receptors such as neuregulin or TGFα, suggesting a role for ER272 as a possible drug to promote neurogenesis in diseases associated with cognitive impairment." (PMID 33335309, 2021). "Although our results suggest that an increase in TGFα may be one of the mechanisms involved in the positive regulation of neurogenesis found in SAMP8 mice avoiding cognitive impairment, we cannot discard the possibility of other signaling molecules being involved in the effect of ER272." (PMID 37177826, 2023).
cyst (2 papers, 2020 to 2021). A sac-like closed membranous structure that may be empty or contain fluid or amorphous material. "This is in line with results showing that the TGFα and EGFR autocrine loops provide a platform for renal-cyst formation." (PMID 32432044, 2020).
endophthalmitis (2 papers, 2018 to 2022). An infectious process affecting the internal structures of the eye. "There was additionally elevated expression of 4 Growth factors including FGF2 (p = 0.000), TGFα (p = 0.000), GCSF (p = 0.000), PDGFAB.BB (p = 0.000), in patients with endophthalmitis when compared to all controls as shown in." (PMID 30296277, 2018).
invasive carcinoma (2 papers, 2014 to 2022). A carcinoma that is not confined to the epithelium, and has spread to the surrounding stroma. "TIMER2.0 was used to identify the correlation between EGFR and other gene expressions in breast-invasive carcinoma subtypes with purity adjustments such as FGF2, FGFBP1, TGFA, TGFBR3, and IGF1R in all BRCA patients." (PMID 36430763, 2022).
kidney tumors (2 papers, 2007 to 2021). "While targeting TGFα with antibodies that block its interaction with the EGFR may inhibit tumor progression, our findings on the molecular forms of TGFα expressed in kidney tumors open a new therapeutic scenario." (PMID 34399807, 2021).
mastitis (2 papers, 2016 to 2023). Inflammation of breast tissue during lactation or postpartum due to an obstructed duct or infection. "Evidence for the presence of EGF in the bovine mammary glands stems from a single study that reported elevated expression for both EGF and TGFA mRNA during mastitis." (PMID 37219601, 2023). "Interestingly, the transcription of both EGF and TGFA was increased during mastitis." (PMID 37219601, 2023).
mesothelioma (2 papers, 1994 to 2020). A usually malignant and aggressive neoplasm of the mesothelium which is often associated with exposure to asbestos. "Besides a potential therapeutic outcome, this report also highlights the clinical relevance of TGFα based on a TCGA dataset of 87 mesothelioma patients." (PMID 32517259, 2020). "TGFα expression and chemosensitivity were further assessed in 10 mesothelioma cell lines." (PMID 32517259, 2020).
metastatic colorectal cancer (2 papers, 2015 to 2017). "However, patient-based data showed a different picture: in metastatic colorectal cancer patients treated with cetuximab, the presence of TGFα positivity correlated with a better outcome." (PMID 27933395, 2017).
nasopharyngeal carcinoma (2 papers, 2024 to 2025). A carcinoma arising from the nasopharyngeal epithelium. "The stimulation of EGFR by TGFα induces sAPPα secretion, leading to increased cell proliferation and motility in nasopharyngeal carcinoma." (PMID 39332525, 2024).
neuroblastoma (2 papers, 2012 to 2018). Neuroblastoma (NB) is the most common solid, extracranial childhood tumor. "In neuroblastoma cells, E2 induced synthesis of transforming growth factor α (TGFα) via ERα, and TGFα in turn, induced cell proliferation." (PMID 29614830, 2018).
sarcopenia (2 papers, 2022). Progressive decline in muscle mass due to aging which results in decreased functional capacity of muscles. "Previous sarcopenia GWAS for European descendants showed association with FTO22,27,28 and several loci, including TGFA and HLA-DRB129." (PMID 35241739, 2022).
ZIKV infection (2 papers, 2018 to 2025). "Second, only four (TGFα, IL-1RA, IL-10, and MCP-1) of 23 assayed serum cytokines demonstrated significant changes following ZIKV infection, similar to findings in related studies." (PMID 30469417, 2018).
acute lymphoblastic leukemia (1 paper, 2024). Leukemia with an acute onset, characterized by the presence of lymphoblasts in the bone marrow and the peripheral blood. "TGFα has been identified as a factor determining worse survival in patients with AML and acute lymphoblastic leukemia (ALL)." (PMID 38673624, 2024).
acute respiratory distress syndrome (1 paper, 2025). Progressive and life-threatening pulmonary distress in the absence of an underlying pulmonary condition, usually following major trauma or surgery. "In patients with acute lung injury/acute respiratory distress syndrome (ALI/ARDS), elevated TGFα levels in pulmonary edema fluid were correlated with their capacity to induce alveolar epithelial repair in vitro." (PMID 40722787, 2025).
AIDS (1 paper, 2020). A syndrome resulting from the acquired deficiency of cellular immunity caused by the human immunodeficiency virus (HIV). "In AIDS, Tr-Gal9, IL-17A, and TGFα showed the high Youden index of more than 1.900." (PMID 33143141, 2020).
allergic asthma (1 paper, 2007). A asthma with a basis in a pathological type I hypersensitivity reaction. "Thus, IL-13-induced, ADAM17-mediated release of TGFα, and subsequent epithelial cell proliferation, could contribute to the epithelial hypertrophy, as well as other features, associated with airway remodeling in allergic asthma." (PMID 17620132, 2007).
brain tumors (1 paper, 2023). "This immunotoxin (TP) comprising TGFα and a modified Pseudomonas exotoxin A (PE38) derived from Pseudomonas aeruginosa was developed for the treatment of EGFR-expressing malignant tumors such as brain tumors." (PMID 36900277, 2023).
breast adenocarcinoma (1 paper, 2019). "Inhibition of the MAPK/ERK pathway after T3 treatment does not interfere with the TGFA gene expression in a breast adenocarcinoma cell line." (PMID 30916164, 2019).
cholestasis (1 paper, 2021). Impairment of the bile flow caused by obstruction within the liver, or outside the liver in the bile duct system. "Further studies are required to better characterize the role of ADAM17 within the liver microenvironment and inflammatory milieu as it pertains to cholangiocyte response, bile duct injury, TGFα, EGFR signaling and overall cholestasis." (PMID 35095853, 2021).
cocaine abuse (1 paper, 2017). Disorders related or resulting from use of cocaine. "This inhibition of neurogenesis might be associated with persistent rewarding memories for cocaine, and therefore, a decreased expression of TGFα might facilitate the persistence of cocaine abuse." (PMID 29038767, 2017).
cocaine addiction (1 paper, 2017). "Although certain factors such as TGFα might contribute to important aspects of cocaine addiction and associated psychiatric comorbidities, the complexity of the interactions of these signaling inflammatory proteins falls beyond our current understanding." (PMID 29038767, 2017). "In any case, the evaluation and validation of TGFα as a suitable candidate for a potential biomarker of both CUD and dual diagnosis could open new research lines for understanding the complexities of cocaine addiction and the associated dual diagnosis." (PMID 29038767, 2017).
cognitive decline (1 paper, 2023). "Our study simultaneously tested a panel of 27 immune markers and showed that IP-10, FGF-2, TGFa and VEGF concentrations in MCI patients were associated with APOE genotype, suggesting their association with cognitive decline in the elderly." (PMID 37686198, 2023).
colorectal tumor (1 paper, 2023). "Studies also have shown that surgical trauma can cause an increase in transforming growth factor α (TGFα), which plays an important role in colorectal tumor invasion and metastasis." (PMID 37161562, 2023).
craniofacial cleft (1 paper, 2023). "Studies demonstrate the interaction of IRF6 and TGFA gene polymorphisms and an increased risk of the craniofacial cleft with their simultaneous presence." (PMID 37020525, 2023).
cytomegalovirus infection (1 paper, 2020). A herpesvirus infection caused by Cytomegalovirus. "The disease occurs in two forms, a childhood form due to cytomegalovirus infection and an adult form attributed to overexpression of transforming growth factor-alpha (TGF-α)." (PMID 33343956, 2020).
demyelinating disease (1 paper, 2025). A broad group of disorders that affect the myelin sheaths that cover the neurons. "Another EGF family member, TGFα, inhibits microglial pyroptosis in demyelinating diseases through the NFκB pathway." (PMID 40292295, 2025).
endometrial tumors (1 paper, 2021). "The concentration of IP-10, PDGF-AA, TGFα, fractalkine, IL-1α, IL-15, IL-13, sCD40L, VEGF, PDGF-BB, IL-17, RANTES, IL-1Ra and IL-8 trended higher in CM from endometrial tumors than that measured in CM from adjacent non-cancerous tissue." (PMID 33968059, 2021).
endometritis (1 paper, 2022). An acute or chronic, usually bacterial infectious process affecting the endometrium. "In the females with endometritis (EN), there were found positive relationships between FSH and the following: inhibin (0.45; p = 0.02), F-T4 (0.66; p = 0.028), F-T3 (0.60; p < 0.05), and TGFα (0.55; p = 0.003)." (PMID 36009715, 2022).
experimental autoimmune encephalomyelitis (1 paper, 2025). An autoimmune demyelinating disease of the central nervous system that is produced experimentally in animals by the injection of homogenized brain or spinal cord in Freund's adjuvant. "We have shown in a previous transcriptome analysis of astrocytes at the peak of experimental autoimmune encephalomyelitis (EAE), an animal model of MS, that microglia-derived TGFα is a key regulator of astrocyte polarization." (PMID 40537468, 2025).
gastric disease (1 paper, 2025). "TGFA/EGFR signaling is not only important for maintaining pit homeostasis but also appears to be responsible for the progression of human gastric disease." (PMID 41365858, 2025). "To verify whether neutralization of TGFA can prevent gastric disease in KO mice, we also implanted the osmotic pumps in 9-month-old Rab25 KO mice." (PMID 41365858, 2025). "Furthermore, long-term exposure to TGFA/EGFR signaling in Rab25 KO mice can induce gastric disease." (PMID 41365858, 2025).